COMT (catechol-O-methyltransferase)
Diseases named in the same sentence as COMT in open-access papers (continued):
Sharing a sentence is not in itself a finding about the gene and the disease.
schizophrenia (continued). "In fact, a recent report demonstrated that individuals homozygous for low enzyme activity alleles of the COMT and MTHFR genes in combination, but not alone, are at increased risk for schizophrenia." (PMID 19365560, 2009). "Some of the potential loci that may be affected by methylation in schizophrenia include SOX 10, COMT and DRD2, but the direct role of the gene specific methylation in schizophrenia has not been established." (PMID 19102774, 2008). "The results do not support a differential COMT gene effect on the deficit/nondeficit subtypes of schizophrenia." (PMID 17173666, 2006). "The expression of COMT does not appear to be altered in the cerebellum of individuals suffering from schizophrenia, bipolar disorder or depression, but does appear to be influenced by single nucleotide polymorphisms within the gene." (PMID 16483362, 2006). "In this study we examined the expression levels of COMT mRNA using quantitative RT-PCR in 60 post mortem cerebellum samples derived from individuals with schizophrenia, bipolar disorder, depression, and no history of psychopathology." (PMID 16483362, 2006). "While the interaction between COMT Val158Met and MAOA uVNTR may be linked to schizotypy, this association has not been found to correlate with the development of schizophrenia in Indian and English populations." (PMID 39595853, 2024). "DNA methylation changes in COMT have not been reported in previous EWAS of schizophrenia." (PMID 38503926, 2024). "The level of COMT mRNA and protein does not appear to be altered in schizophrenia." (PMID 36833173, 2023). "In various studies, only a few of them, such as DISC1 (Disrupted-In-Schizophrenia 1), COMT (Catechol-O-Methyltransferase), VMAT1 (Vesicular Monoamine Transporter 1) or NRG1 (Neuregulin 1), could be sufficiently confirmed as relevant for schizophrenia development." (PMID 35053755, 2021). "More recent work has confirmed such epistatic gene-gene interactions, for instance, by showing that COMT and DRD3 together modulate behavior in children with ADHD and that DRD4 in combination with COMT modulate the clinical responses to clozapine in schizophrenia patients." (PMID 33328916, 2020). "Thus, future studies of epistatic interactions between genes such as COMT and AKT1 might help in elucidating the relationship between schizophrenia and cancer that has been discussed in epidemiological studies." (PMID 20520724, 2010). "However, in contrast to schizophrenia, idiopathic PD did not interact with the effects of val158met COMT genotype." (PMID 18755526, 2010). "Therefore, the genetic interaction of the COMT Val158Met and MTHFR C677T genotype may contribute to executive function deficits in schizophrenia." (PMID 21217836, 2010). "Deficit schizophrenia was observed in one female: COMT genetic variation has been previously shown to produce sexual dimorphism in brain dopamine levels; we repeated the analyses comparing COMT genotype between deficit and nondeficit subtypes in males only." (PMID 17173666, 2006). "Interestingly, the catechol-O-methyltransferase (COMT) gene, crucial for DA degradation in the brain, along the 5-HT2A receptor gene that is crucial in serotonin signaling, were studied for their roles in ADHD, schizophrenia, mood regulation, and aggressive behavior." (PMID 39337894, 2024). "Based on this data, it may be speculated that genetically-induced higher COMT activity may be related to higher levels of anticipatory anhedonia, measured by the BNSS and RSAS, but not physical anhedonia, assessed by the RPAS, in female patients with schizophrenia." (PMID 34287249, 2021). "Some papers reported that more homozygous Val/Val in catechol-O-methyltransferase (COMT) Val158Met genotypes were found (31 vs. 17%) in the non-deficit schizophrenia patients compared to the deficit schizophrenia subgroup, and SNP8NRG241930 in NRG1 were associated with non-deficit schizophrenia." (PMID 29156812, 2017).
schizophrenia (continued). "The frequency of the COMT rs4680 (χ2 = 0.046; df = 1; p = 0.829) or the COMT rs4818 (χ2 = 0.523; df = 1; p = 0.469) genotypes did not deviate from HWE in patients with schizophrenia." (PMID 32572118, 2020). "Further research would therefore benefit from a longitudinal approach, investigating the interaction between proline and COMT on the change in negative symptoms assessed via the SANS or Positive and Negative Symptom Scale, in a large sample of both schizophrenia and bipolar disorder patients." (PMID 27622935, 2016).
Parkinson disease (128 papers, 2009 to 2026). A progressive degenerative disorder of the central nervous system characterized by loss of dopamine producing neurons in the substantia nigra and the presence of Lewy bodies in the substantia nigra and locus coeruleus. "This study implicates a potential role of catechol-O-methyltransferase-mediated dopamine metabolism in the early olfactory impairments associated with Parkinson’s disease." (PMID 40024917, 2025). "By blocking the breakdown of dopamine, COMT inhibitors increase the amount of dopamine available in the brain, which helps to improve the motor symptoms associated with Parkinson's disease." (PMID 37841347, 2023). "Responsible for the O-methylation of molecules with catechol moieties, such as the neurotransmitter dopamine, COMT has been linked to several neurodegenerative disorders, with Parkinson’s disease being one of the most studied." (PMID 36293152, 2022). "A few neurological conditions such as migraine and Parkinson’s disease have also been studied to determine their association with COMT variants." (PMID 34725583, 2021). "Some studies have investigated the role of COMT genotype polymorphisms in response to treatment for neurological and psychiatric diseases like Parkinson’s and ADHD." (PMID 34725583, 2021). "A study in 2015 indicated that polymorphism in the COMT gene was associated with Parkinson's disease in a Japanese population." (PMID 33282008, 2020). "Further study on COMT confirmed that such gene turns out to be one of the potential pathogenic gene for Parkinson disease, validating the efficacy and accuracy of our prediction." (PMID 29258237, 2017). "The catechol‐O‐methyltransferase (COMT) gene is involved in brain catecholamine metabolism, but its association with Parkinson's disease (PD) risk remains unclear." (PMID 40988463, 2025). "COMT rs4680 genotype has been shown to be associated with pain sensitivity in patients treated with morphine after cardiac surgery, and with pain severity in Parkinson's disease patients and hospitalized burn victims." (PMID 35401282, 2022). "COMT gene polymorphism influenced working memory in Parkinson’s disease." (PMID 34725583, 2021). "Recent studies have found that the functional catechol-O-methyltransferase (COMT) gene may be associated with the susceptibility to and pharmacotherapy of Parkinson’s disease (PD)." (PMID 28451382, 2017). "Alternatively, it might be resulted from a combination of early age at onset of Parkinson's disease, disease duration, and COMT deficiency." (PMID 27017469, 2016). "In collaboration with Weinberger's group, and in the context of the Cambridgeshire Parkinson's Incidence from GP to Neurologist (CamPaIGN) cohort study which we elaborate on later, 288 PD patients stratified by COMT polymorphism were assessed, focusing in particular on the CANTAB SoC test." (PMID 23038420, 2013). "That COMT has been implicated in multiple disorders i.e. major depressive disorder, Parkinson's and pain, might be deemed as a weakness in its candidacy for a placebo response marker." (PMID 23110189, 2012). "The COMT enzyme is involved in a wide variety of physiological processes, such as prefrontal cortex function and lipid metabolism, and has been implicated in diseases such as schizophrenia, pain sensitivity, Parkinson's disease, and cancer." (PMID 21304959, 2011). "We investigated whether the val158met functional polymorphism of catechol-o-methyltransferase influenced age-related changes in grey matter density and volume, both in healthy individuals (n = 80, ages 18–79) and those with Parkinson's disease (n = 50)." (PMID 18755526, 2010). "Tolcapone, a drug commonly used in the treatment of Parkinson’s disease, is a potent inhibitor of Catechol-O-methyltransferase (COMT) and is permeable across the blood–brain barrier." (PMID 40725140, 2025).
Parkinson disease (continued). "Due to the major implication of catecholamine metabolism and COMT inhibitors in Parkinson’s disease management, these results prompted us to investigate EAPB02303 bioactivation by COMT." (PMID 40490448, 2025). "Entacapone, COMT inhibitor approved for Parkinson’s disease, likely exerts its protective effects through dopaminergic modulation, a pathway closely linked to cognitive function and neurodegeneration." (PMID 41510304, 2025). "COMT inhibitors are frequently used as adjunctive therapy to extend the effects of l-DOPA in Parkinson’s disease." (PMID 40024917, 2025). "Entacapone is a COMT inhibitor that improves motor symptoms and quality of life in Parkinson's disease patients by inhibiting COMT enzyme activity, prolonging the half‐life of levodopa, and enhancing its action time in the central nervous system." (PMID 40260643, 2025). "Tolcapone is a COMT inhibitor used in the treatment of Parkinson’s disease, and it enhances dopamine signaling in prefrontal cortical networks." (PMID 40430486, 2025). "It is a well-known target in Parkinson’s disease, where the COMT inhibitors entacapone, tolcapone and opicapone are used in combination with levodopa to increase its half-life and potentiate its effect." (PMID 40490448, 2025). "Entacapone, a specific inhibitor of catechol-O-methyltransferase (COMT), has long been used as an adjunctive treatment for Parkinson’s disease." (PMID 41425591, 2025). "Catechol-O-methyltransferase inhibitors (COMT-Is) have significantly improved the quality of life and symptom management for those at advanced stages of Parkinson’s Disease (PD)." (PMID 39338193, 2024). "Currently, COMT inhibitors are used in clinical practice in combination with levodopa for the treatment of Parkinson’s disease." (PMID 38641695, 2024). "We previously researched the chemical properties of Korean bee pollen and their catechol-O-methyltransferase inhibitory activities, indicating their potential prevention and treatment of Parkinson’s disease and depression." (PMID 39199227, 2024). "Entacapone, a COMT (catechol-O-methyltransferase) inhibitor used in Parkinson’s disease management, showed a potent and selective inhibition of c-Met receptor in the current study." (PMID 39728413, 2024). "When used in combination with levodopa, COMT inhibitors have been shown to reduce the amount of “off” time experienced by patients with advanced Parkinson's disease, as well as increase the amount of “on” time and reduce the required dose of levodopa." (PMID 37841347, 2023). "Anti‐Parkinson's disease agents with distinct mechanisms of action include catechol‐O‐methyl transferase (COMT) inhibitors, such as entacapone and opicapone." (PMID 37340511, 2023). "The leaves of C. officinalis and the isolated compounds exhibited remarkable COMT inhibitory activities, indicating their utility as bioactive ingredients toward Parkinson’s disease." (PMID 36770999, 2023). "They inhibit the COMT enzyme and are frequently used in the treatment of Parkinson’s disease as an adjunct to levodopa/carbidopa medication." (PMID 36840015, 2023). "Recent studies showed that entacapone, a catechol‐o‐methyl transferase (COMT) inhibitor currently applied for Parkinson's disease, can inhibit FTO enzyme." (PMID 36534072, 2023). "Levodopa (L-dopa) and catechol-O-methyltransferase (COMT) inhibition are widely used therapeutics in Parkinson’s disease (PD)." (PMID 36839259, 2023). "Entacapone, one of the most common drugs distributed among patients with Parkinson’s disease, is a peripherally acting catechol-O-methyltransferase (COMT) inhibitor that is used in addition to levodopa to control symptoms." (PMID 35463646, 2022). "Tolcapone (Tasmar, 3,4-dihydroxy-4′-methyl-5-nitrobenzophenone)is a potent inhibitor of catechol-O-methyltransferase(COMT) approved in the United States and Europe as an adjunct to levodopaand carbidopa for the treatment of Parkinson’s disease." (PMID 36306808, 2022).
Parkinson disease (continued). "These promising results prompt additional biophysical and structural studies in order to better characterize the protein COMT as a viable anti-Parkinson’s disease target." (PMID 36293152, 2022). "Entacapone and tolcapone are both inhibitors of catechol-O-methyltransferase (COMT), used in the treatment of Parkinson's disease as an adjunct to levodopa/carbidopa therapy." (PMID 35568032, 2022). "Nowadays, the inhibition of COMT is seen as a viable option to treat Parkinson’s disease and, in combination with levodopa, different inhibitors have been proposed for this purpose." (PMID 36293152, 2022). "The V158M polymorphism of the COMT = low enzymatic activity and ↑ dopamine levels in the CNS = this can cause or aggravate EPS in these patients (including parkinsonism, akathisia, dystonia, and dyskinesia)." (PMID 35745668, 2022). "Parkinson’s disease is treated with levodopa, carbidopa, amantadine, rotigotine, dopamine agonists, Catechol-O-methyltransferase (COMT) inhibitors, anticholinergics Selegiline, rasagiline, safinamide, etc." (PMID 36263141, 2022). "Due to its role as a key regulator of dopamine in the prefrontal cortex, a brain region that processes pain signaling, COMT has been investigated extensively in the context of depression and Parkinson's disease." (PMID 35401282, 2022). "Dopamine plays a role in the pathophysiology of Parkinson's disease, and the COMT enzyme degrades dopamine." (PMID 34725583, 2021). "A pharmacophore-based virtual screening methodology was used to discover new catechol-O-methyltransferase (COMT) inhibitors with interest in Parkinson’s disease therapy." (PMID 35056108, 2021). "In particular, inhibition of peripheral COMT offers a unique advantage, since COMT inhibitors are clinically used as adjunct to levodopa (L-dopa) for the treatment of Parkinson’s disease." (PMID 34030574, 2021). "Entacapone was initially approved by the FDA as a COMT inhibitor for the treatment of Parkinson’s disease." (PMID 34017338, 2021). "Inhibition of catechol-O-methyltransferase (COMT) is an established strategy for treating end-of-dose motor fluctuations (wearing-off) in patients with Parkinson’s disease (PD) treated with levodopa (L-dopa) and a DOPA decarboxylase inhibitor (DCI)." (PMID 33630140, 2021). "Entacapone was previously considered to be a catechol-O-methyltransferase (COMT) inhibitor for the treatment of Parkinson’s disease." (PMID 34017338, 2021). "Like tafamidis, the catechol-O-methyltransferase (COMT) inhibitor tolcapone, approved for the treatment of Parkinson’s disease, has a TTR stabilizing effect with a greater capacity to cross the blood–brain barrier." (PMID 34719408, 2021). "The drug Tolcapone (registered as TASMAR), an orally active catechol-O-methyltransferase (COMT) inhibitor approved for Parkinson’s disease, is also an efficient TTR tetramer stabilizer and has been repurposed for FAP and for cerebral amyloidosis." (PMID 33348885, 2020). "Opicapone, a once daily COMT inhibitor, was licensed in Europe in 2016 and the United States in 2020 as an adjunctive drug to l‐dopa in patients with Parkinson's disease and end‐of‐dose motor fluctuations." (PMID 33163567, 2020). "The drug tolcapone, an orally active catechol-O-methyltransferase (COMT) inhibitor authorized in the United States and Europe as an adjunct to levodopa and carbidopa for the treatment of Parkinson’s disease, has also been repurposed for FAP." (PMID 32998442, 2020). "We applied our selection system on catechol O-methyltransferase (Comt), a known drug target for treating Parkinson's disease." (PMID 30856169, 2019). "The current pharmacological treatments for Parkinson’s disease only offer symptomatic relief to the patients and are based on the administration of levodopa and catechol-O-methyltransferase or monoamine oxidase-B inhibitors (IMAO-B)." (PMID 31336891, 2019). "In the brain, COMT is involved in mental processes, as studies have reported for Parkinson's disease." (PMID 30693065, 2018).